BRAF (B-Raf proto-oncogene, serine/threonine kinase)
Diseases named in the same sentence as BRAF in open-access papers (continued):
Sharing a sentence is not in itself a finding about the gene and the disease.
melanoma (continued). "Similarly, an altered expression of CSF-1R was found in resistant melanoma cells with BRAF and MAPKs mutations." (PMID 38254773, 2024). "Understanding the BRAF mutation status has become standard practice in diagnosing melanoma." (PMID 38891988, 2024). "Often, class III BRAF mutants in tumors co-exist with RAS mutations or neurofibromin 1 (NF1) deletions (melanomas) or RTK upregulation (lung and colorectal cancers), highlighting the need for concurrent mechanisms for sustaining RAS activation despite ERK-dependent feedback." (PMID 38731852, 2024). "However, the development of potent and selective inhibitors such as vemurafenib, dabrafenib, and encorafenib, which target mutated BRAF, has been the major breakthrough in melanoma treatment." (PMID 38474231, 2024). "The prognostic importance of the BRAF V600E mutation in advanced melanoma remains unclear, with multiple studies having variably linked its presence to survival outcomes, with a recent meta-analysis demonstrating significant heterogeneity between studies." (PMID 38884085, 2024). "However, the ways in which these drugs inhibit activity under the two major activating mutations in melanoma, BRAF V600E and NRAS Q61 hotspot mutations, and the corresponding drug dose landscape are still being explored." (PMID 39199684, 2024). "Additionally, molecular profiling plays a key role in the diagnosis and staging of melanoma, as AM cells often exhibit distinct genetic mutations; for instance, in the BRAF, NRAS, and c-KIT genes." (PMID 39519055, 2024). "Our panel sequencing identified 58 patients (7 CM, 40 AM, and 11 MM) with potentially actionable mutations amenable to approved or off‐label drug targeting, along with 31 patients (27 CM and 4 AM) with melanoma with clinically detectable BRAF V600E/K mutations." (PMID 39564955, 2024). "In addition, NRAS mutations are prevalent in approximately 25% of melanoma and display an even more aggressive tumour progression than their BRAF-mutated counterparts, although the role of NRAS mutations only serve as a prognostic factor." (PMID 38127894, 2024). "Key genetic drivers central to melanoma development, such as mutations in the BRAF, NRAS, and c-KIT genes, are discussed alongside the latest WHO classification, which categorizes melanomas based on cumulative sun damage (CSD), which correlates with specific molecular alterations." (PMID 38474231, 2024). "Therefore, while CTHRC1 and the BRAF(V600E) mutation serve as diagnostic and prognostic biomarkers in melanoma, they cannot simply be considered oncogenic biomarkers and exhibit tissue specificity." (PMID 39052013, 2024). "Whereas most institutions routinely test high-risk patients with melanoma for actionable BRAF mutations, expansion of the routine genetic panel used may facilitate the application of risk stratification and treatment decisions based on specific mutations." (PMID 38158497, 2024). "One of the main reasons for the high aggressiveness of melanoma is the occurrence of a mutated form of serine-threonine kinase BRAF, a component of the mitogen-activated protein kinase (MAPK) signaling pathway, which is detected in about 50% of patients suffering from cutaneous melanoma." (PMID 39175042, 2024). "BRAF mutations are found in more than half of patients with melanoma." (PMID 39682109, 2024). "Importantly, combination therapy involving RAF and MEK pathway inhibition has become the standard of care for melanoma cancers demonstrating BRAF mutations." (PMID 39123450, 2024). "Similarly, trametinib, the MEK inhibitor use in the treatment of human melanoma, especially those with BRAF mutations, has shown efficacy in trials, suggesting similar pathway inhibition." (PMID 39408717, 2024). "In addition, when melanomas are classified into BRAF‐mutant, RAS‐mutant, NF1‐loss, and triple wild type, about half of CM cases have BRAF mutations, while only 10%–20% of AM and MM cases have them." (PMID 38087810, 2024).
melanoma (continued). "Additionally, approximately 10% of melanomas are caused by gene mutations, with BRAF being an example." (PMID 38519031, 2024). "Furthermore, liquid biopsy of BRAF V600E mutation can be suggestive of resistance after melanoma patient receiving Vemurafenib treatment." (PMID 38310289, 2024). "Similarly, BRAF inhibitors such as vemurafenib have shown efficacy in melanoma patients with BRAF V600E mutations, further emphasizing the role of genomic markers in guiding therapy." (PMID 39727835, 2024). "Targeted therapy is used for melanomas with specific genetic mutations, such as the BRAF mutation." (PMID 39335684, 2024). "Because CNMs+ melanomas appear to be associated with the BRAF V600E mutation, the presence of CNMs could have cancer predictive significance for identifying a subgroup of patients who might benefit from specific biologic drugs." (PMID 39099686, 2024). "Treatment strategies for melanoma depend on the BRAF mutation status and staging." (PMID 39717410, 2024). "Taken together, we show that intratumoral stimulation of RIG-I with its synthetic ligand 3pRNA in combination with the clinically relevant BRAF/MEK double inhibition outperforms the therapeutic effect of the individual therapies against BRAF-mutated melanoma in vivo." (PMID 39165562, 2024). "BRAF gene is mutated in 40–50% of melanomas and its role in melanoma development is paramount." (PMID 39727691, 2024). "The logistic regression method for predicting BRAF mutation in melanoma samples revealed a relatively weak correlation (AUROClog15 = 0.69; 95% CІ: 0.63–0.75) between BRAF status and 15 variables, although the model was adequate (χ2 = 35.5 at 20 degrees of freedom, p < 0.001)." (PMID 39735251, 2024). "Despite all these achievements, it remains unclear if BRAF mutation is associated with any specific melanoma stage." (PMID 38541077, 2024). "The question of whether RIPK4 levels affect cisplatin sensitivity more in melanoma cells with BRAF mutations than in those with NRAS or BRAF wild-type mutations warrants further investigation in future studies." (PMID 39766280, 2024). "Throughout this review, we have explored the genetic landscape of melanoma, highlighting the importance of mutations in key genes such as BRAF, NRAS, and KIT, as well as the relevance of epigenetic modifications and interactions with the tumor microenvironment." (PMID 39200315, 2024). "Additionally, the association between BRAF mutation and rapid disease progression has led to the development of BRAF inhibitors, representing a significant advancement in melanoma treatment." (PMID 38891988, 2024). "Given of the common genomic variants of BRAF in many solid carcinomas, such as melanoma and lung cancer, the treatment of this variant in other solid tumors may have some indicative price." (PMID 38241570, 2024). "Furthermore, the mutation status of the BRAF gene and the use of BRAF inhibitors both influence the oxidative metabolism and oxidative phosphorylation levels of melanoma cells, potentially determining their sensitivity to ferroptosis inducers." (PMID 39430757, 2024). "Therefore, we used these cell lines as experimental models to investigate the effects of RICTOR/mTORC2 depletion in the response of BRAF-mutated melanoma cells to BRAF/MEKi." (PMID 38755661, 2024). "Furthermore, the therapy of BRAF-mutated melanoma with the ENOX2 inhibitor PXD for preventing the development of resistance to targeted therapies is investigated." (PMID 39519404, 2024). "Furthermore, the correlation between CTHRC1 expression and the BRAF(V600E) mutation in colon cancer, thyroid cancer, and melanoma was analyzed." (PMID 39052013, 2024). "Almost 50% of melanomas show the activation of BRAF mutations." (PMID 38201012, 2024).
melanoma (continued). "In melanoma, the most frequent CNAs were observed in BRAF and previous studies suggested that an increased BRAF copy number could be associated with disease progression." (PMID 38674331, 2024). "This retrospective study investigated outcomes of anti‐programmed death receptor‐1 monotherapy and targeted therapy in the first‐line setting in patients with metastatic BRAF‐mutated melanoma, focusing on clinical and laboratory parameters associated with treatment outcome." (PMID 38491825, 2024). "The discovery of a BRAF mutation, consisting of the substitution of V600E valine for glutamic acid at codon 600 that constitutively activates the MAPK (mitogen-activated protein kinase) pathway in more than 60% of melanomas, led to the use of BRAF inhibitors (BRAFi) targeting this mutation." (PMID 38339003, 2024). "This co-occurrence suggests that PTEN loss may contribute to the resistance to BRAF inhibitors, a common therapy for melanoma." (PMID 39200315, 2024). "In consideration of the clinical implications of our results, the suppression of the oncogenic MAPK pathway by BRAF or MEK inhibitors may be a useful molecular targeted drug for cancer metastasis in BRAFV600E/PTEN loss melanoma." (PMID 38233537, 2024). "On the other hand, reovirus predominantly replicated in NRAS- and BRAF-mutated melanoma cells." (PMID 39772250, 2024). "In some cases such as advanced melanoma, the presence of a BRAF mutation actually improves patient prognostic outlook, while in other types such as colorectal cancer, the finding of a BRAF V600E mutation is associated with resistance to standard therapy and is overall a biomarker of poor prognosis." (PMID 38539548, 2024). "Thus, development of inhibitors of NRAS would address a critical unmet need to treating primary tumors harboring NRAS mutations as well as BRAF-mutant melanomas, which frequently develop resistance to clinically approved BRAF inhibitors through NRAS mutation." (PMID 39379700, 2024). "Therefore, it is crucial to study the molecular mechanisms involved in the BRAF(V600E) mutation in human colon cancer, thyroid cancer, and melanoma." (PMID 39052013, 2024). "This novel class I RAF-selective inhibitor is indicated as monotherapy in the treatment of adults with an inoperable or metastatic form of melanoma with a positive BRAF V600 mutation, as it not only improves the survival rate but has also demonstrated a 60% antitumor response rate in these patients." (PMID 39797148, 2024). "Melanoma tumor tissue samples for BRAF mutation analysis were available in 52 patients (65%)." (PMID 39387479, 2024). "BRAF is the most commonly mutated gene in up to 50% of melanomas." (PMID 39335684, 2024). "BRAF mutations are found in approximately 40–60% of melanoma cases." (PMID 38203795, 2024). "The evasion of immune response has been associated with BRAF mutations “affecting signaling pathways in melanoma development.”194 Abnormal BRAF kinase activity occurs in approximately half of CMs owing to point mutations at codon 600, with the replacement of glutamic acid for valine." (PMID 38831791, 2024). "Based on these notions, we have hypothesized that RICTOR/mTORC2 deficiency in BRAFV600E melanoma cells may favor BRAF/MEKi resistance." (PMID 38755661, 2024). "Moreover, we now understand that the presence of common gene mutations usually found in regular nevi and melanoma, such as BRAF mutations, exclude a diagnosis of Spitz lesion." (PMID 38791877, 2024). "While cases with BRAF TCGA driver mutations alone were consistent with previously reported data suggesting a predominance of class I mutations in BRAF mutant melanoma, only one of eleven BRAF co-mutated cases (co-occurring with either NRAS or NF1) exhibited a class I BRAF mutation." (PMID 38611025, 2024).
melanoma (continued). "The prognostic impact of age, gender, ethnicity, melanoma subtype, M category (extent of distant metastasis), BRAF mutational status, cKIT mutational status, PD1 inhibitor therapy and the use of non-PD1 inhibitor systemic therapies on overall survival was analysed." (PMID 39125477, 2024). "Finally, the BRAF inhibitor, vemurafenib, further potentiated the effects of the combined statin–dipyridamole treatment in BRAF V600E mutation-bearing human melanoma cell lines." (PMID 38540310, 2024). "Thus, we investigated the effects of ABT-737 and ABT-263, which target Bcl-2, Bcl-xL and Bcl-w as well as the Bcl-2-selective ABT-199 and the Mcl-1-selective S63845, in a panel of four BRAF-mutated and BRAF-WT melanoma cell lines." (PMID 38542429, 2024). "In addition, NRAS mutations frequently arise in BRAF-mutant melanomas as a mechanism of resistance in response to pharmacological inhibition of BRAF." (PMID 39379700, 2024). "Regarding melanoma, telomere length correlates positivelywith patient survival; however, telomere dysfunction and associated genome destabilization delay tumor development in BRAF V600E mutated mice." (PMID 39519202, 2024). "Moreover, in melanoma cells with BRAF and NRAS mutations, HSPB8 exerts this role through the induction of autophagy, which counteracts cell growth." (PMID 38775220, 2024). "Among all melanoma cases, roughly half contain at least one BRAF-activating mutation." (PMID 38473384, 2024). "Notably, BRAF-mutated melanoma are associated with shorter survivals in both metastatic and early-stage patients." (PMID 39086722, 2024). "However, the exact role of BRAF mutations in the initiation or progression of melanoma is still controversial." (PMID 38396984, 2024). "Vemurafenib was among the pioneering BRAF inhibitors approved for treating BRAF-mutated melanoma." (PMID 39582535, 2024). "Importantly, this pathway is rewired, and a new optimum is established in BRAF-mutated melanoma cells in response to therapy with BRAF or MEK inhibitors." (PMID 39436655, 2024). "Furthermore, 15% of NF1 loss-of-function mutant melanomas harbor concomitant class III C600 BRAF mutations." (PMID 39727691, 2024). "Two clinical studies, COMBI-d and COMBI-v, conducted on patients with metastasized melanoma and BRAF V600E and V600K mutations, showed a 5-year overall survival rate of 34% and a median overall survival time of 25.9 months with dabrafenib plus trametinib treatment." (PMID 39204387, 2024). "The first case was a 15-year-old boy with malignant melanoma with BRAF fusion mutation." (PMID 38470950, 2024). "Although the dual inhibition of BRAF and MEK by their specific inhibitors has demonstrated significant treatment successes in advanced melanoma in patients with the BRAF mutation, most patients showed only short response durations along with the development of both intrinsic and acquired resistance." (PMID 38334632, 2024). "Mutations in the BRAF gene cause about 50% of melanomas, notably BRAF-V600E." (PMID 39682188, 2024). "Importantly, BRAF mutation and expression can also modulate the immunological phenotypes of melanoma." (PMID 39086722, 2024). "Typically, NF1 mutations are found in melanomas that lack mutations of BRAF and NRAS." (PMID 38247727, 2024). "Several BRAF mutations have been identified, the most common being the substitution from valine to glutamate at codon 600 (V600E), which accounts for over 90% of BRAF mutations in melanoma." (PMID 39199653, 2024). "Current clinical standards for BRAF-mutated melanoma use a combination of B-Raf and MEK inhibitors." (PMID 39018206, 2024). "Three out of four patients who died from melanoma had either BRAF V600 or NRAS mutations." (PMID 38890171, 2024). "However, fewer studies have attempted to develop a BRAF mutation-associated gene risk model for predicting the prognosis of melanoma." (PMID 37205993, 2023).
melanoma (continued). "Although BRAFV600E is considered a promising therapeutic target for several cancers, especially for BRAF mutation-harboring melanoma, the BRAF inhibitor monotherapy was less effective than anticipated in clinical trials of patients with PTC harboring the BRAFV600E mutation." (PMID 36624452, 2023). "However, despite these promising results, almost all patients (diagnosed with BRAF-mutated advanced melanoma) experience tumour relapse within several months after initiation of combined treatment." (PMID 37627054, 2023). "Melanoma patients often have multiple genetic mutations, with BRAF mutations being the most common." (PMID 37745303, 2023). "The preliminary indication of antitumor activity in BRAF-mutated melanoma is promising although further clinical development of single agent use in this setting in tumors that do not harbor RAF fusions (e.g., those with KRAS or NRAS mutations) is likely to be limited." (PMID 37219686, 2023). "By building a protein-protein interaction (PPI) network and doing a functional enrichment analysis, we were able to pinpoint the gene CYTL1, which may be crucial to the emergence and development of melanoma with BRAF mutations." (PMID 37745303, 2023). "Genomic classification based on the pattern of the most prevalent significantly mutated genes identified four distinct subtypes of melanoma, including mutant BRAF (n = 114), mutant RAS (mainly NRAS, n = 81), mutant NF1(n = 23), and Triple-WT (wild-type, n = 36)." (PMID 38082384, 2023). "The inactivation of PTEN in BRAF-mutated nevus may represent a leading step in the complex process of nevus to melanoma transformation, thus NAM formation." (PMID 36834954, 2023). "Therefore, it mediates selective cytotoxicity in BRAF-mutated melanoma in vitro and prevents tumor progression in vivo, providing a basis for melanoma therapy." (PMID 37836558, 2023). "However, most of the published literature on the clinical use of liquid biopsy to detect patients with BRAF mutation concerns maily mCRC, melanoma and NSCLC, while few data are available on less frequent types of cancer." (PMID 37542343, 2023). "Interestingly, inhibition of TERT reduced growth of BRAF-mutated melanoma including resistant cells." (PMID 37296851, 2023). "This pathway enhances melanoma cells to overcome oxidative stress caused by BRAF/MEK inhibitors." (PMID 36678596, 2023). "Thus, combinations of BRAF and MEK inhibitors have developed as a standard therapy for BRAF-mutated melanoma, and resulted in improved long-term clinical outcomes." (PMID 36902392, 2023). "Finally, the study showed in 17 melanoma samples with the V600 BRAF mutation that resistance to BRAFi and suppression of tumor growth was induced by miR-181a/b targeting TFAM and inhibiting its expression." (PMID 36982460, 2023). "Since the discovery of the first actionable mutation (BRAF V600), several other putative drivers of melanomagenesis and/or melanoma progression have been identified, and others are currently being assessed, prompting pharmacogenomics studies on potentially actionable targets." (PMID 36901733, 2023). "Point mutations of EZH2 result in a gain-of-function in 5% of melanomas and are often found in coexistence with activating BRAF mutations, which may indicate an oncogenic synergism." (PMID 37370834, 2023). "Notably, the treatment combination of an MEK inhibitor with a BRAF inhibitor in BRAF-mutant melanoma cells caused high ROS production, both in vitro and in vivo." (PMID 37189846, 2023). "Then, cobimetinib (MEK inhibitor), trametinib (MEK inhibitor), and dabrafenib (BRAF inhibitor) was approved by FDA to treat melanoma with BRAFV600 mutations, and trametinib and dabrafenib could also treat NSCLC with BRAFV600E mutation." (PMID 37345194, 2023). "Approximately 80% of melanomas contain either BRAF or NRAS activating mutations." (PMID 36588164, 2023). "PAK1 is amplified and overexpressed in melanoma, and it is strongly associated with wild-type BRAF." (PMID 36830998, 2023).